BMAL2 (basic helix-loop-helix ARNT like 2)
Description:
Transcriptional activator which forms a core component of the circadian clock. The circadian clock, an internal time-keeping system, regulates various physiological processes through the generation of approximately 24 hour circadian rhythms in gene expression, which are translated into rhythms in metabolism and behavior. It is derived from the Latin roots 'circa' (about) and 'diem' (day) and acts as an important regulator of a wide array of physiological functions including metabolism, sleep, body temperature, blood pressure, endocrine, immune, cardiovascular, and renal function. Consists of two major components: the central clock, residing in the suprachiasmatic nucleus (SCN) of the brain, and the peripheral clocks that are present in nearly every tissue and organ system. Both the central and peripheral clocks can be reset by environmental cues, also known as Zeitgebers (German for 'timegivers'). The predominant Zeitgeber for the central clock is light, which is sensed by retina and signals directly to the SCN. The central clock entrains the peripheral clocks through neuronal and hormonal signals, body temperature and feeding-related cues, aligning all clocks with the external light/dark cycle. Circadian rhythms allow an organism to achieve temporal homeostasis with its environment at the molecular level by regulating gene expression to create a peak of protein expression once every 24 hours to control when a particular physiological process is most active with respect to the solar day. Transcription and translation of core clock components (CLOCK, NPAS2, BMAL1, BMAL2, PER1, PER2, PER3, CRY1 and CRY2) plays a critical role in rhythm generation, whereas delays imposed by post-translational modifications (PTMs) are important for determining the period (tau) of the rhythms (tau refers to the period of a rhythm and is the length, in time, of one complete cycle). A diurnal rhythm is synchronized with the day/night cycle, while the ultradian and infradian rhythms have a period shorter and longer than 24 hours, respectively. Disruptions in the circadian rhythms contribute to the pathology of cardiovascular diseases, cancer, metabolic syndromes and aging. A transcription/translation feedback loop (TTFL) forms the core of the molecular circadian clock mechanism. Transcription factors, CLOCK or NPAS2 and BMAL1 or BMAL2, form the positive limb of the feedback loop, act in the form of a heterodimer and activate the transcription of core clock genes and clock-controlled genes (involved in key metabolic processes), harboring E-box elements (5'-CACGTG-3') within their promoters. The core clock genes: PER1/2/3 and CRY1/2 which are transcriptional repressors form the negative limb of the feedback loop and interact with the CLOCK|NPAS2-BMAL1|BMAL2 heterodimer inhibiting its activity and thereby negatively regulating their own expression. This heterodimer also activates nuclear receptors NR1D1/2 and RORA/B/G, which form a second feedback loop and which activate and repress BMAL1 transcription, respectively. The CLOCK-BMAL2 heterodimer activates the transcription of SERPINE1/PAI1 and BHLHE40/DEC1.
Synonyms: CLIF; bHLHe6; ARNTL2; MOP9; PASD9
Tractability: PROTAC: UniProt records ubiquitination sites on it.
Gene: Protein-coding gene on chromosome 12 (27,332,836 to 27,425,289, forward strand). Ensembl gene ENSG00000029153.
Subcellular location: Nucleus
Subcellular location (Human Protein Atlas): Nucleoli; Nucleoplasm
Pathways (Reactome):
Circadian clock: BMAL1:CLOCK,NPAS2 activates circadian expression
Gene Ontology:
Molecular function: DNA-binding transcription factor activity; DNA-binding transcription factor activity, RNA polymerase II-specific; E-box binding; protein binding; RNA polymerase II cis-regulatory region sequence-specific DNA binding; protein dimerization activity
Biological process: circadian regulation of gene expression; circadian rhythm; positive regulation of circadian rhythm; positive regulation of DNA-templated transcription; positive regulation of transcription by RNA polymerase II; regulation of transcription by RNA polymerase II; entrainment of circadian clock; regulation of DNA-templated transcription
Cellular component: CLOCK-BMAL transcription complex; nucleolus; nucleoplasm; nucleus; aryl hydrocarbon receptor complex; chromatin; cytoplasm; transcription regulator complex
Genetic constraint (gnomAD): Loss-of-function variants: 30 observed, 48.97 expected, observed/expected ratio (o/e) 0.61, 90% interval 0.46 to 0.83. The upper end of that interval is the gene's LOEUF score, 0.83, which puts it in group 3 of 6, group 1 being the genes least tolerant of losing a copy. Missense variants: 496 observed, 580.12 expected, observed/expected ratio (o/e) 0.86, 90% interval 0.79 to 0.92. Synonymous variants: 187 observed, 193.06 expected, observed/expected ratio (o/e) 0.97, 90% interval 0.86 to 1.09.
Homologues: Orthologues: chimpanzee ARNTL2 (99% identical), macaque ARNTL2 (96% identical), dog ARNTL2 (81% identical), pig BMAL2 (74% identical), rabbit BMAL2 (69% identical), rat Bmal2 (68% identical), mouse Bmal2 (66% identical), tropical clawed frog bmal2 (54% identical), zebrafish bmal2 (50% identical), Drosophila melanogaster tgo (27% identical), Caenorhabditis elegans aha-1 (20% identical), Drosophila melanogaster gce (17% identical), and 2 more. Paralogues in human: BMAL1 (48% identical), ARNT (31% identical), ARNT2 (30% identical), CLOCK (22% identical), NPAS2 (20% identical), PASD1 (7% identical).
Diseases named in the same sentence as BMAL2 in open-access papers:
BMAL2 is named in the same sentence as 60 diseases in open-access papers, as found by Europe PMC text mining. Sharing a sentence is not in itself a finding about the gene and the disease. The quoted sentences say what the papers report.
pancreatic cancer (13 papers, 2019 to 2025). "A pre-publication report indicates that BMAL2 supports hypoxic responses in a pancreatic cancer model 45, so it could also play a role in ccRCC." (PMID 39070610, 2024).
breast cancer (12 papers, 2013 to 2026). A primary or metastatic malignant neoplasm involving the breast. "BMAL2 has been implicated as an oncogenic driver in multiple human cancers, including lung, colorectal, and breast cancer, where it can drive tumorigenesis and create an immunosuppressive micro‐environment for advanced tumor growth." (PMID 40948103, 2026). "In the subjects with three night shifts, SNPs in BMAL1 (rs2278749), BMAL2 (rs2306074), CSNK1E (rs5757037), NPAS2 (rs17024926), PER3 (rs1012477) and MTNR1A (rs131113549) were associated with decreased breast cancer risk." (PMID 23822714, 2013). "In addition, women in this exposure group carrying at least one variant allele of several SNPs in the other core circadian genes such as BMAL2, CSNK1E, NPAS2 and PER3 had a noteworthy reduced risk of breast cancer." (PMID 23822714, 2013).
glioma (4 papers, 2022 to 2024). A benign or malignant brain and spinal cord tumor that arises from glial cells (astrocytes, oligodendrocytes, ependymal cells). "Major mutated CRGs in LGG are PER2, BMAL1, CLOCK and BMAL2, which might indicate these genes are most influencial CRGs to glioma development or metastasis." (PMID 39043735, 2024).
type 1 diabetes (4 papers, 2013 to 2021). "The Bmal2 gene is considered to be associated with type 1 diabetes in non-obese mice." (PMID 24086613, 2013).
Obesity (3 papers, 2022 to 2023). Accumulation of substantial excess body fat. "A Western blot analysis of sWAT samples from normal-weight, obese, and weight-loss (WL) donors revealed that the BMAL2 protein was solely elevated by WL compared to BMAL1; demonstrating that BMAL2 is a WL-regulated adipogenesis inhibitor may aid in the development of strategies to combat obesity." (PMID 37626963, 2023).
type 2 diabetes (2 papers, 2019 to 2026). "The Bmal2 rs7958822 genotype shows a significant association with type 2 diabetes (T2DM) among obese Japanese individuals." (PMID 31139087, 2019).
coagulation disorders (1 paper, 2022). "Among these, BMAL2 regulates the transcription of anticoagulant thrombomodulin and PAI-1 by forming a heterodimer with CLOCK; therefore, abnormal expression of BMAL2 may cause coagulation disorders." (PMID 36561297, 2022).
prostate carcinoma (1 paper, 2026). A carcinoma that arises from epithelial cells of the prostate gland. "Importantly, two key circadian‐regulating transcription factors, Bmal2 and Rev‐erbβ, exhibited upregulated expression patterns in TGMAP tumors throughout the 12‐h light/dark cycles, suggesting their potential roles in the growth of advanced prostate cancer." (PMID 40948103, 2026).
Sepsis (1 paper, 2024). Sepsis is defined as life-threatening organ dysfunction caused by a dysregulated host response to infection. "Our data elucidate the pivotal role of BMAL2 and address the critical question of how DAMPs induce macrophage endotoxin tolerance in the context of sepsis." (PMID 38938563, 2024). "These collective insights highlight the importance of BMAL2 in the intricate interplay between circadian rhythms and immune responses, shedding light on a previously overlooked aspect of the molecular clock machinery and its implications in sepsis pathogenesis." (PMID 38938563, 2024). "eCIRP upregulates BMAL2 expression via TREM-1, leading to macrophage endotoxin tolerance in sepsis." (PMID 38938563, 2024).
cancer (23 papers, 2016 to 2026). A tumor composed of atypical neoplastic, often pleomorphic cells that invade other tissues. "Comparing to these proteins, the involvement and molecular mechanisms of another circadian rhythms gene, named Bmal2 (ARNTL2), was less clear in the development of malignant tumors." (PMID 37003979, 2023).
BMAL2 also shares sentences with these, for which no sentence is quoted: tumor (33 papers); lung adenocarcinoma (15); lung carcinoma (9); pancreatic ductal adenocarcinoma (7); colorectal cancer (6); colon carcinoma (4); clear cell renal cell carcinoma (3); depression (3); Anxiety (2); autism (2); lymph node metastasis (2); neurodevelopmental disorder (2); rheumatoid arthritis (2); social phobia (2); acute myocardial infarction (1); adrenocortical carcinoma (1); alcohol abuse (1); allergic disease (1); Alzheimer disease (1); aneurysm (1); atopic dermatitis (1); autoimmune disease (1); Autoimmunity (1); bipolar disorder (1); cataract (1); cervical cancer (1); cervical squamous cell carcinoma (1); diabetes (1); hepatocellular carcinoma (1); inflammatory bowel disease (1).
A further 20 diseases each share a sentence with BMAL2 in 1 paper.